RBM15 (RNA binding motif protein 15)
Diseases named in the same sentence as RBM15 in open-access papers (continued):
Sharing a sentence is not in itself a finding about the gene and the disease.
cancer (57 papers, 2013 to 2026). A tumor composed of atypical neoplastic, often pleomorphic cells that invade other tissues. "Nuclear export control: RBM15 facilitates nuclear export of specific cancer-associated mRNAs, ensuring proper subcellular localization and subsequent protein expression." (PMID 41403702, 2025). "Forest plot showed that high expression of RBM15 was associated with DSS in patients with 7 types of cancer, including ACC, KICH, KIRC KIRP, LGG, PAAD and PRAD." (PMID 35223996, 2022). "The GO and KEGG pathway analysis showed RBM15 alteration was associated with immune and cancer related signaling pathways." (PMID 35223996, 2022). "GO and KEGG analysis showed RBM15 alteration was significantly associated with cancer and immune related signaling pathways, such as “cell division”, “T cell receptor signaling pathway” and “Cell cycle”." (PMID 35223996, 2022). "RBM15 is abnormally up-regulated and significantly associated with poor prognosis and immune infiltration in several cancer types, particularly in PAAD." (PMID 35223996, 2022). "In this study, we first analyzed genomic alterations of RBM15 in human pan-cancer and found that there were mutations or copy number variations in RBM15 genome." (PMID 35223996, 2022). "Results showed that high expression of RBM15 was associated with poor prognosis in several cancer types, particularly in PAAD." (PMID 35223996, 2022). "RBM15 expression was associated with patients’ DFI in 8 cancer types, including ACC, BLCA, CESC, CHOL, KIRP, LIHC, PAAD and UCEC." (PMID 35223996, 2022). "Survival analysis suggested high expression of RBM15 was associated with poor prognosis in many cancer types." (PMID 35223996, 2022). "Thus, by precisely controlling the distribution and levels of m6A modification, RBM15 plays a pivotal role in epitranscriptomic regulation and profoundly affects the expression and function of cancer-associated genes." (PMID 41403702, 2025). "Pan-cancer analysis revealed mutations or copy number variations of RBM15 in 25 cancer types, with high expression significantly associated with overall survival (OS), disease-free interval (DFI), progression-free interval (PFI), and disease-specific survival (DSS)." (PMID 41403702, 2025). "In this study, we found that RBM15 is mutated and copy number varied in 25 cancer types." (PMID 35223996, 2022). "Furthermore, 175 RBM15 mutations were identified across various cancers, 146 (83.4%) were missense, 28 (16%) were truncating and 1 (0.6%) was SV/Fusion." (PMID 35223996, 2022). "This study shows that RBM15 has mutations and copy number variations in human pan-cancer." (PMID 35223996, 2022). "The results showed that RBM15 was mutated or copy number varied in 25 types of cancer." (PMID 35223996, 2022). "Second, RBM15 is aberrantly upregulated in various cancers but displays relatively low expression in normal tissues." (PMID 41403702, 2025). "Previous reviews on RBM15 have primarily focused on its roles in cancer biology, with limited discussion of its functions in the immune system." (PMID 41403702, 2025). "In fact, RBM15 has been reported to participate in multiple key biological processes during cancer development." (PMID 41403702, 2025). "At the biomarker level, accumulating evidence indicates that aberrant RBM15 expression strongly correlates with patient prognosis across multiple cancers." (PMID 41403702, 2025). "RBM15, as an important m6A RNA methyltransferase, plays a critical role in tumorigenesis and progression across various cancer types." (PMID 41403702, 2025). "While ample evidence supports the role of RBM15 in oncogenesis, these studies primarily focus on alterations in cancer cells within immunocompromised environments." (PMID 40370450, 2025). "Previous research has indicated that RNA N6-methyladenosine (m6A) methyltransferase RNA-binding motif protein-15 (RBM15) is involved in various cancers." (PMID 39840822, 2025).
cancer (continued). "Dysregulated RBM15 expression has been observed across various cancer types, correlating with poor prognosis and therapy resistance." (PMID 41403702, 2025). "Although the role of RBM15 in cancer initiation and progression has been well established, its mechanisms in immune regulation are still poorly understood." (PMID 41403702, 2025). "RBM15 plays a pivotal role in the progression of various cancers through diverse molecular mechanisms." (PMID 41256854, 2025). "As a universal regulator of m6A RNA methylation, RBM15 has been reported to be dysregulated in various human cancers, including COAD." (PMID 40883807, 2025). "As a critical regulator of m6A methylation, RBM15 is aberrantly upregulated in various cancers and correlates with poor prognosis." (PMID 41403702, 2025). "Taken together, RBM15 serves as a crucial link between epitranscriptomic regulation and cancer biology, exerting multilayered functions through diverse mechanisms." (PMID 41403702, 2025). "A previous study has shown that RBM15 knockdown in HEK293 human cancer cell lines increases protein levels of the SWI/SNF subunit SMARCC158." (PMID 40447637, 2025). "This upregulation also alleviated the inhibitory effects of RBM15 downregulation on NSCLC cancer cell growth." (PMID 39716068, 2024). "Although the impact of m6A modifications on cancer has garnered widespread attention, RBM15 has been relatively overlooked." (PMID 38915367, 2024). "Recent studies have extensively reported that MTCs, including RBM15, play a crucial role in the development of various cancers." (PMID 38915367, 2024). "The research demonstrates that RBM15 controls genes involved in the cancer metabolism of serine and glycine, two types of amino acids, which contributes to cancer cell proliferation." (PMID 38825643, 2024). "We further investigated the effects of the interplay and the underlying mechanisms between circ‐CTNNB1 and RBM15 on the regulation of target genes (GPI, HK2 and PGK1) and cancer progression in OS cells." (PMID 36181462, 2023). "Of them, TARBP1, KIAA1429, MTEEL3, RBM15, RBM15B, and TARBP1 had extensive somatic mutation among pan-cancers." (PMID 36707911, 2023). "In this study, based on the RNA-seq data of 16 cancer types in the TCGA database, we analyzed the prognostic ability of m6A regulators in pan-cancer and found that RBM15 was the most significant adverse survival factor among 20 m6A regulators." (PMID 36232485, 2022). "In this study, we found that RBM15 is mutated or has copy number variation and significantly correlated with MMR gene mutations across many cancer types." (PMID 35223996, 2022). "Together, these results provide clues for further investigation of the mechanism of RBM15 in cancer." (PMID 35223996, 2022). "Pan-cancer analysis reveals that TC m6A genes are disproportionately differentially expressed, alongside with altered RBM15/B expression, suggesting that disruption of this stable m6A layer may contribute to transcriptional changes in cancer." (PMID 41890104, 2026). "Future studies focusing on RBM15-targeted interventions, either alone or in combination with immunotherapy, may provide novel strategies for precision cancer treatment." (PMID 41403702, 2025). "In addition, the UALCAN database exhibited that RBM15 was elevated in the sample types, individual cancer stages, nodal metastatic status, and histologic subtypes of COAD." (PMID 39840822, 2025). "The expression and function of RBM15 are finely regulated by diverse upstream signals and epigenetic modifications, and these regulatory mechanisms display considerable variability across different cancer types." (PMID 41403702, 2025). "In recent years, the role of RBM15 in various cancers has attracted significant attention." (PMID 40370450, 2025). "Therefore, RBM15 functions not only as a pivotal molecular regulator in cancer development but also as a promising therapeutic target for potential clinical intervention." (PMID 41403702, 2025).
cancer (continued). "This might be due to the fact that RBM15 influences the formation of malignant tumors via a variety of molecular processes." (PMID 38436027, 2024). "Hence, to determine the therapeutic efficacy of RBM15 targeting, we targeted RBM15 using a siRNA-mediated delivery method, which is widely used for gene knockdown in cancer cells." (PMID 38825643, 2024). "Thus, RBM15 coordinates cancer cell growth through altered serine and glycine metabolism, suggesting that RBM15 is a new therapeutic target in BC." (PMID 38825643, 2024). "RBM15, in particular, has been shown to play an oncogenic role in various cancers." (PMID 39716068, 2024). "Importantly, overexpression of RBM15 confers resistance to commonly used chemotherapeutic agents in cancers, including paclitaxel and docetaxel." (PMID 39039611, 2024). "RBM15 promoted the invasion, migration and metastasis of OS with a high correlation with metastasis and the decreased survival rate, and m6A regulators were confirmed to play vital roles in regulating glycolysis of cancer cells." (PMID 36181462, 2023). "As shown by reports, RBM15 is vital to the development of cancer." (PMID 37761904, 2023). "Next, we studied the RBM15 expression in cancer and paracancerous tissues." (PMID 36831430, 2023). "All these results indicate RBM15 exists genomic alterations in many cancers." (PMID 35223996, 2022). "Taken together, pan-cancer analysis of RBM15 suggested it may be served as a prognostic biomarker and immunotherapeutic target for PAAD." (PMID 35223996, 2022). "RBM15 mRNA was abnormally up-regulated across various cancers." (PMID 35223996, 2022). "The previous studies all suggest RBM15 may be abnormally expressed in cancers and affect cancer development and progression." (PMID 35223996, 2022). "Our study sheds light on a possible role of RBM15 in different cancers, suggesting that RBM15 may be a potential prognostic and immunological biomarker in PAAD." (PMID 35223996, 2022). "Additionally, RBM15 was abnormally high expressed in 25 cancers and correlated with patients’ poor prognosis and immunity in PAAD." (PMID 35223996, 2022). "Firstly, we analyzed genomic alterations of RBM15 gene in 32 cancers by cBioPortal database." (PMID 35223996, 2022). "The significant role of RBM15 in malignant cancer progression has been confirmed in many studies." (PMID 36232485, 2022). "Interestingly, RBM15 exhibits a contrasting role in certain cancers." (PMID 41256854, 2025). "In addition, RBM15 also regulates cancer through signaling pathways or other modifications." (PMID 38915367, 2024). "Recent evidence underscores the pivotal role of RBM15 in cancer, where it predominantly functions as a methyltransferase, enhancing the stability of target mRNAs through m6A modification, thereby contributing to the initiation and progression of diverse cancers." (PMID 38915367, 2024). "Thus, the development of selective RBM15 inhibitors that are effective against cancer is possible." (PMID 38825643, 2024). "Studies have shown that elevated RBM15 expression emerged as a significant contributor to unfavorable prognosis, and conversely, the suppression of the RBM15 demonstrates the potential to inhibit cancer cell proliferation, invasion, and metastasis to varying extents." (PMID 38915367, 2024). "In CC, RBM15 drives m6A modification and protein translation of EZH2, leading to enhanced cancer cell proliferation, invasiveness, and epithelial-mesenchymal transition (EMT)." (PMID 41256854, 2025). "IGF2BP2, IGF2BP3, RBM15, WTAP, and YTHDC2 are positively correlated to the immune score in a few cancer types." (PMID 39457524, 2024). "Therefore, targeting RBM15, which contributes to serine and glycine metabolism as an upstream regulator, could be a good alternative therapeutic approach to control serine and glycine metabolism for cancer treatment." (PMID 38825643, 2024).
cancer (continued). "We further validated this by examining RBM15 expression levels, observing a marked increase in NSCLC cancer tissues compared to normal tissues (p < 0.01)." (PMID 39716068, 2024). "In cancer cells, we found that MUC1-C decreases expression of (i) RBM15/B, (ii) WTAP, and (iii) METTL3/14." (PMID 38740827, 2024). "We believe that the cancer-promoting role of ECE2 gene is related to the modification of m6A, which may affect the methylation level of LUAD, especially HNRNPC, through its association with HNRNPC, IGF2BP1, IGF2BP3 or RBM15, and ultimately affect the progression of LUAD." (PMID 36299451, 2022). "Our results showed that RBM15 and RBM15B were significantly up-regulated in NSCLC samples and had frequent CNV alterations, indicating their potential role in promoting cancer cell migration and invasion." (PMID 36591468, 2022). "For example, lncRNA PCAT6 bound to RBM15 and IGF2BP3 in several cancer cell lines, which were determined by CLIP and eCLIP technology." (PMID 36032659, 2022). "However, the role of RBM15 in human different cancers remains unknown." (PMID 35223996, 2022). "While some members play the opposite role, promoting cell proliferation and the invasion of cancer, including RBM7, RBM11, and RBM15." (PMID 34804951, 2021). "Other RBM proteins family members also participate in promoting proliferation in various cancers, such as RBM5-AS1, RBM11, RBM15, RBM23, RBM33, etc.." (PMID 34804951, 2021). "For example, the RNA splicing and processing theme involves 2,009 pSNVs in 652 genes, including 38 known cancer genes such as BRCA1, RBM15, CDK12, CDC73 and TOP1 (FDR p = 1.3e − 06, Fisher's exact test), as well as candidate cancer genes." (PMID 24089029, 2013). "RBM15 functions not in isolation but within cooperative regulatory networks involving epigenetic factors and transcription factors, amplifying its role in cancer progression." (PMID 41403702, 2025). "In NSCLC, RBM15 up-regulates Kruppel-like factor 1 (KLF1), which suppresses the expression of TRIM13, a member of the tripartite motif (TRIM) family, and promotes ANXA8, a member of the annexin A (ANXA) family, thereby accelerating cancer progression." (PMID 41256854, 2025). "In NSCLC cancer tissues, RBM15 expression was positively correlated with KLF1 and negatively correlated with TRIM13 (p < 0.01)." (PMID 39716068, 2024). "Although we focused on RBM15 and serine metabolism in this study, network analysis revealed that the relationship between RBM15 and other genes with oncogenic potential (CDC42, CDC14B, STK40, BRD3, CPNE1, and MCM3) is also crucial for cancer cell survival." (PMID 38825643, 2024). "Of note, the expression levels of RBM15 and RBFOX2 were positively correlated in cancer patients." (PMID 38915367, 2024). "Although RBM15 has been extensively studied in LSCC, its roles in pan-cancer and whether it can be used as a biomarker remains unclear." (PMID 35223996, 2022). "Although the role of RBM15 in LSCC is well understood, it’s functions in human pan-cancer remains largely unknown." (PMID 35223996, 2022). "Compared with the control group, expression levels of HNRNPC, YTHDF1, KIAA1429, RBM15, YTHDF2, and METTL3 in cancer group were significantly up-regulated (P < 0.05), while expression levels of FTO, ZC3H13, METTL14, YTHDC1, and WTAP in cancer group were significantly down-regulated (P < 0.05)." (PMID 33193582, 2020). "However, the precise role of RBM15 as an m6A regulator in these processes, including cancer, has not been studied in detail." (PMID 38825643, 2024). "In conclusion, akin to METTL3, METTL4, METTL16, WTAP, RBM15/15B, VIRMA, and ZC3H13, the potential influence of YTHDC1, YTHDC2, YTHDF, IGF2BPs, the HNRNP family, eIF3, FTO, and ALKBH3/5 on autophagy is intertwined with their roles in RNA metabolism, collectively regulating autophagy in cancer." (PMID 38148841, 2023).
cancer (continued). "RBM15 is a member of the SPEN (split‐end) family of proteins, which interacts with RNA by binding with spliceosome components, playing vital roles in the mechanism of mRNA methylation as a m6A methyltransferase ‘writer’,37 and exerting oncogenic role in cancer." (PMID 36181462, 2023). "These defects were initially not retained in our filtering, because known cancer genes (NRAS, BCL10, TRIM33, RBM15) are also included in the same deletion and the minimal mutational frequency requirement was not satisfied." (PMID 28147343, 2017). "Furthermore, IHC assays were performed to determine the localization of RBM15 in LSCC tissue and its expression in 122 pairs of matched cancer tissues and adjacent non-cancerous tissues." (PMID 33637103, 2021).
hematological malignancies (5 papers, 2021 to 2025). "However, the role of RBM15 in CVDs was rarely reported, and only a few studies linked it to some blood disorders." (PMID 36819785, 2023). "The high expression of RBM15 could stimulate Notch signaling by RBPJk, and the enhancement of Notch signaling was associated with hematological malignancies." (PMID 35433701, 2022). "From the analysis on the “Total” data set IGF2BP1, ALKBH5, IGF2BP2, RBM15, METTL3, ZNF217 is the potentially carcinogenic gene in hematological malignancies." (PMID 33816257, 2021).
metabolic disease (3 papers, 2023 to 2025). A congenital disorder (due to inherited enzyme abnormality) or acquired (due to failure of a metabolically important organ) disorder resulting from an abnormal metabolic process. "Overall, our study has demonstrated that the offspring of GDM mom is much easier to develop metabolic disorders in which RBM15 might play an important role." (PMID 36803098, 2023).
infection (2 papers, 2021 to 2023). The state of being infected such as from the introduction of a foreign agent such as serum, vaccine, antigenic substance or organism. "Transcriptome analyses showed that infection with influenza A virus upregulated the expression level of WTAP (two of six experiments) but downregulated METTL3, RBM15, and VIRMA (one of six experiments, each)." (PMID 34502037, 2021).
digestive system cancer (1 paper, 2025). A primary or metastatic malignant neoplasm involving any part of the digestive system. "We further explored whether RBM15 plays a role in immunomodulation in other digestive system cancers." (PMID 40370450, 2025).
RBM15 also shares sentences with these, for which no sentence is quoted: bladder cancer (4 papers); non-small cell lung carcinoma (4); gestational diabetes mellitus (3); head and neck squamous cell carcinoma (3); atherosclerosis (2); acute erythroid leukemia (1); Acute myelomonocytic leukemia (1); acute promyelocytic leukemia (1); adenomyosis (1); adrenocortical carcinoma (1); asthma (1); bacterial infection (1); cardiovascular disease (1); colorectal adenocarcinoma (1); cutaneous melanoma (1); End-Stage Renal Failure (1); endometriosis (1); Hepatic steatosis (1); hepatitis C (1); hyperplasia (1); hypothyroidism (1); influenza (1); lymphopenia (1); mental retardation (1); metabolic syndrome (1); Myelodysplasia (1); myeloid neoplasm (1); nonalcoholic fatty liver disease (1); portal hypertension (1); preeclampsia (1).
A further 5 diseases each share a sentence with RBM15 in 1 paper.